TRIM63 (tripartite motif containing 63)
Description:
E3 ubiquitin ligase. Mediates the ubiquitination and subsequent proteasomal degradation of CKM, GMEB1 and HIBADH. Regulates the proteasomal degradation of muscle proteins under amino acid starvation, where muscle protein is catabolized to provide other organs with amino acids. Inhibits de novo skeletal muscle protein synthesis under amino acid starvation. Regulates proteasomal degradation of cardiac troponin I/TNNI3 and probably of other sarcomeric-associated proteins. May play a role in striated muscle atrophy and hypertrophy by regulating an anti-hypertrophic PKC-mediated signaling pathway. May regulate the organization of myofibrils through TTN in muscle cells.
Synonyms: MuRF-1; MuRF1; IRF; RNF28; SMRZ; CMH31; MURF2
Tractability: No criterion of Open Targets' tractability assessment is met for any kind of drug.
Gene: Protein-coding gene on chromosome 1 (26,051,301 to 26,068,436, reverse strand). Ensembl gene ENSG00000158022.
Subcellular location: Cytoplasm; Nucleus; Cytoplasm, myofibril, sarcomere, M line; Cytoplasm, myofibril, sarcomere, Z line
Pathways (Reactome):
Gene expression (Transcription): FOXO-mediated transcription of oxidative stress, metabolic and neuronal genes
Immune System: Antigen processing: Ubiquitination & Proteasome degradation
Gene Ontology:
Molecular function: protein binding; titin binding; ubiquitin protein ligase activity; ubiquitin-protein transferase activity; zinc ion binding
Biological process: negative regulation of glycolytic process; innate immune response; response to electrical stimulus involved in regulation of muscle adaptation; signal transduction; negative regulation of cardiac muscle hypertrophy; protein ubiquitination; response to glucocorticoid; response to interleukin-1; skeletal muscle atrophy
Cellular component: cytoplasm; M band; Z disc; microtubule; nucleus; contractile muscle fiber
Genetic constraint (gnomAD): Loss-of-function variants: 43 observed, 41.73 expected, observed/expected ratio (o/e) 1.03, 90% interval 0.81 to 1.33. The upper end of that interval is the gene's LOEUF score, 1.33, which puts it in group 5 of 6, group 1 being the genes least tolerant of losing a copy. Missense variants: 438 observed, 433.37 expected, observed/expected ratio (o/e) 1.01, 90% interval 0.93 to 1.09. Synonymous variants: 168 observed, 164.35 expected, observed/expected ratio (o/e) 1.02, 90% interval 0.9 to 1.16.
Gene-disease validity (ClinGen):
ClinGen rates the evidence that TRIM63 causes each of these diseases.
hypertrophic cardiomyopathy (autosomal recessive): Moderate. A condition in which the myocardium is hypertrophied without an obvious cause.
hypertrophic cardiomyopathy (autosomal dominant): Disputed.
Homologues: Orthologues: chimpanzee TRIM63 (99% identical), macaque TRIM63 (98% identical), dog TRIM63 (94% identical), pig TRIM63 (94% identical), mouse Trim63 (92% identical), rat Trim63 (91% identical), rabbit TRIM63 (91% identical), guinea pig TRIM63 (87% identical), tropical clawed frog trim63 (65% identical). Paralogues in human: TRIM55 (59% identical), TRIM54 (58% identical), MID2 (21% identical), TRIM46 (21% identical), MID1 (21% identical), TRIM36 (21% identical), TRIM9 (19% identical), TRIM13 (19% identical), TRIM47 (19% identical), TRIM7 (19% identical), TRIM25 (19% identical), TRIM67 (19% identical), and 68 more.
Diseases named in the same sentence as TRIM63 in open-access papers:
TRIM63 is named in the same sentence as 152 diseases in open-access papers, as found by Europe PMC text mining. Sharing a sentence is not in itself a finding about the gene and the disease. The quoted sentences say what the papers report.
muscle atrophy (136 papers, 2009 to 2026). The loss of muscle tissue due to inactivity or disease. "Muscle atrophy causes apparent muscle degradation, and the tripartite motif containing 63 (Trim63) and F-box only protein 32 (Fbxo32) are the most intensively studied E3 ubiquitin-protein ligases and are upregulated in atrophy models." (PMID 36139912, 2022). "Mice deficient for MuRF1/Trim63 and atrogin-1/Fbxo32 are protected against various forms of muscle atrophy and pharmacological inhibition of MuRF1 has been shown to attenuate muscle atrophy." (PMID 35615361, 2022). "Well-accepted ‘atrogenes’, Atrogin-1 (Fbxo32) and Murf1 (Trim63) encoding muscle atrophy F-Box/atrogin-1 (MAFbx) and muscle-specific RING-finger protein 1 (MuRF1) belonging to ubiquitin–proteasomal pathway, are highly expressed in multiple models of muscle atrophy both in mRNA and protein levels." (PMID 35725651, 2022). "We conducted an immunohistochemical analysis to evaluate the immunoreactivities of anti-FBXO32, anti-TRIM63, and anti-FoxO3a markers involved in diabetic skeletal muscle atrophy." (PMID 38020198, 2023). "Induction of TRIM63 has been observed in immobilisation-induced muscle atrophy but the length of surgery in the present study is unlikely to have been sufficient to induce atrophy." (PMID 29454501, 2019). "Furthermore, their downstream genes such as FBXO32, TRIM63, CTSL, and BNIP3, which have been associated with skeletal muscle atrophy in humans and mice, were found to be significantly upregulated in G. parasuis-infected skeletal muscle." (PMID 38540418, 2024). "Our results demonstrate that increases in the mRNA levels of Fbxo32 and Trim63 E3 ligases are sufficient to manifest a reduction in the CSA, the gold standard for detecting muscle atrophy." (PMID 40331994, 2025). "For instance, animal models of muscle atrophy demonstrated a consistent increase in the gene expression of FBXO32 (ATROGIN1) and TRIM63 (MURF1), which are part of the ubiquitin proteasome pathway involved in protein degradation." (PMID 31498843, 2019). "Experimental studies have associated increased expression of the pro-apoptotic ubiquitin proteasome E-3 ligases MuRF1 (aka TRIM 63) and MAFbx (aka Atrogin-1 or Fbxo32) with statin myalgia and muscle atrophy." (PMID 28771594, 2017).
Atrophy (122 papers, 2005 to 2025). Any weakening or degeneration, especially through lack of use. "The two main E3 ligases associated with atrophy are the RING E3 ligases MuRF1/TRIM63 and Atrogin-1/MAFbx." (PMID 39201486, 2024). "In UPS, the most well-known ubiquitin enzymes associated with muscle atrophy are two E3 ubiquitin-protein ligases, TRIM63 (Tripartite Motif Containing 63, or MuRF1), and FBXO32 (F-box only protein 32, or atrogin 1)." (PMID 35891702, 2022). "Their expressions are increased transcriptionally under various atrophy conditions, and mice deficient in either MuRF1/Trim63 or atrogin-1/Fbxo32 were observed to be resistant to atrophy." (PMID 35276908, 2022). "Numerous studies showed that the tripartite motif-containing 63 (TRIM63) gene expression, encoding MuRF1, is increased rapidly and strongly during various physiological and pathological atrophy conditions." (PMID 33519497, 2020). "Three key mRNAs in muscle loss are muscle RING finger-1 (MuRF1, also called Trim63), muscle atrophy F-box (MAFbx, also called Fbxo32 and Atrogin-1), and Caspase 3, all upregulated in numerous rodent models of muscular atrophy including disease, immobilization, hind limb unloading, and spaceflight." (PMID 30906768, 2019). "As already mentioned, TRIM63/MuRF1 mRNA and protein expression are rapidly and strongly increased in various physiological and pathological atrophy conditions." (PMID 34572540, 2021). "Our results suggest that the activation of the Fbxo32 and Trim63 transcription can be achieved by different combinations of activators and co-activators in response to distinct atrophy stimuli." (PMID 29717119, 2018). "In concordance with many other atrophy models, there was an early (0.25-4d) and maintained (5-8d) 2-fold up-regulation of the muscle-specific E3 ligases, atrogin-1/Fbox32 and Murf1/Trim63, and a slightly decreased expression at the longest duration (9-14d)." (PMID 22165895, 2011). "However, we found that atrophy-related genes (e.g., Trim63 and Fbxo32) were highly expressed in the adult synaptic region compared with the P0 synaptic region." (PMID 33933147, 2021). "Both glucocorticoids and UVB are treatment modalities in psoriasis, and expression of the TRIM63 gene in skin from RSV treated mice may indicate a step towards atrophy, which in the case of IMQ induced thickening of the skin, may be beneficial." (PMID 25965695, 2015). "A further feature reported in a number of different models of diseases resulting in muscle atrophy is the substantial up-regulation of two E3 ubiquitin ligases, atrogin-1/MAFbx (FBXO32) and MuRF1 (TRIM63), which are generally induced early during the atrophy process." (PMID 19400950, 2009). "To define whether the reduced size of the Sam68−/− fibers is accompanied by features of atrophy, we analyzed the expression levels of two atrophy-related genes: the ubiquitin ligases Fbxo32 (MAFbx/atrogin-1) and Trim63 (muscle RING-finger 1, MuRF1)." (PMID 32753528, 2020). "For example, animal models of muscle atrophy demonstrated a consistent increase in expression of FBXO32 and TRIM63 but the same results have not been consistently confirmed in human studies." (PMID 31498843, 2019).
sarcopenia (86 papers, 2009 to 2026). Progressive decline in muscle mass due to aging which results in decreased functional capacity of muscles. "Of note, the results of this study indicated that TRIM63, a crucial regulator of sarcopenia, is linked to skeletal muscle atrophy but also to the pathological process of IDD by regulating ACE ubiquitination degradation." (PMID 40520007, 2025). "On the basis of these findings, we hypothesize that the TRIM63-ACE regulatory axis may represent an important pathological mechanism in sarcopenia-associated IDD, a hypothesis that requires verification through further mechanistic studies." (PMID 40520007, 2025). "These cytokines, viz., IL-6, TNF-α, and IL-1β, activate muscle-specific protein degradation pathways through E3 ubiquitin ligases TRIM63 and FBXO32, linking NSCLC progression to cancer-associated sarcopenia." (PMID 42278237, 2026). "The RNA‐seq results showed that NTs significantly downregulated the expression of sarcopenia‐related genes (Trim63, Dkk3 and Mt1)." (PMID 40745399, 2025). "Here we identified Dkk3 as the key secreted factor generated by muscles to induce sarcopenia and characterized the mechanism of Dkk3-dependent transcription activation of Fbxo32 and Trim63." (PMID 29717119, 2018). "This similarity indicates that TRIM63 could serve as an important molecular bridge connecting sarcopenia and IDD." (PMID 40520007, 2025). "Like TRIM63, we expected that TRIM27 might also play an important role in osteoporosis or sarcopenia, skeletal diseases characterized by the loss of bone and muscle mass." (PMID 40251491, 2025). "Because no clear patterns of gene expression emerged based on disease, we conclude that the type of disease does not dictate direction of change for FBXO32 or TRIM63 in the context of cachexia/sarcopenia." (PMID 31498843, 2019). "Of note, no consistent results in the expression of FBXO32 and TRIM63, rather not increased, have been obtained in studies of human sarcopenia, suggesting that sarcopenia may be developed through different pathways from the relatively acute muscular atrophy." (PMID 40623060, 2025).
Cachexia (76 papers, 2010 to 2026). Severe weight loss, wasting of muscle, loss of appetite, and general debility related to a chronic disease. "To further validate cachexia development using established molecular markers of muscle wasting, we examined the expression of genes that encode ubiquitin ligases associated with muscle proteolysis (Trim63/MuRF1, Fbxo32/MAFBx, Fbxo31, Fbxo30/Musa1)." (PMID 31861290, 2019). "The ubiquitin ligases Trim63 and Fbxo32, which are associated with inflammation-induced muscle atrophy and cachexia, remained within normal levels, suggesting that the induction of the autophagocytic pathway was specific to mitochondria rather than a general increase in the catabolic pathway." (PMID 29127187, 2018). "Among these, muscle RING finger-containing protein 1 (MURF1, also known as TRIM63) and muscle atrophy F box protein (MAFbx, also known as Atrogin-1) are defined as muscle-specific E3 ubiquitin ligases and are the most widely studied in the case of cachexia-associated muscle loss." (PMID 32195193, 2020). "Nevertheless, the association between IGF1 and cancer growth has raised several concerns, while several other mediators have been identified as key mediators of the cachexia process (i.e., Atrogin1 (MAFbx) and MuRF1 (Trim63))." (PMID 38334644, 2024). "Representative UPS proteins, such as MAFbx/Fbxo32 and MuRF1/Trim63, have been shown to be highly active in cancer cachexia." (PMID 39624846, 2024). "The E3 ubiquitin ligases Atrogin1 (MAFbx) and MuRF1 (Trim63) are key factors involved in the development of cachexia, with a prominent role in promoting proteolysis." (PMID 38334644, 2024). "On the molecular level, cachexia is often determined through the assessment of muscle atrogenes, most prominently Atrogin 1 (F-Box Protein 32/Fbxo32) and MuRF1 (Muscle-Specific RING Finger Protein 1, also called Tripartite Motif Containing 63/Trim63)." (PMID 35008253, 2021). "NF-κB was shown to target Trim63 in skeletal muscle in cachexia and the present work supports these data in atrophying muscle due to unloading, although we show a role for p50 and Bcl-3 rather than involvement of p65." (PMID 21249144, 2011). "Ubiquitin E3 ligases, Fbxo32/atrogin‐1/Mafbx and Trim63/MuRF1, were increased in the diaphragm at the time of cachexia onset (D12), supporting their involvement in muscle fibre atrophy, but declined thereafter, showing significant transcriptional repression at endpoint." (PMID 39810606, 2025). "The up-regulation of UBB, FBXO32 (atrogin-1) and TRIM63 (MuRF1) in the irradiated and cachectic muscle tissue suggested that radiation-induced cachexia may share a similar pathway to other muscular atrophic conditions." (PMID 27029502, 2016). "In the current study we used qRT-PCR to measure components of these pathways, as well as the atrophy biomarkers atrogin-1/Fbxo32 and MuRF1/Trim63, to determine whether the response of muscle to human PC cells is similar to syngeneic murine models of cancer cachexia." (PMID 27901481, 2017). "Gene-expression analysis by qPCR in different skeletal muscles showed increased expression of atrophy-related genes (MAFbx/Atrogin-1, Trim63/MuRF-1, Foxo-1) and the pro-inflammatory gene TNF-α, also known as cachectin, as additional sign of cachexia." (PMID 35013221, 2022). "Studies have shown that muscle RING-type E3 ubiquitin ligase 1 (MuRF1, TRIM63) and muscle atrophy F-box protein (MaFbx) in the ubiquitin–proteasome pathway are closely related to the degradation of muscle protein in cachexia patients." (PMID 34724970, 2021). "Trim63 and Fbxo32 expression was increased by 2.3 fold and 1.4 fold, respectively, in CT26-bearing cachexia mice without IDH1 mutation." (PMID 37741882, 2023). "The expression levels of muscle-specific ubiquitin ligases, such as Atrogin-1/MAFbx, MuRF1/TRIM63, SMART, have been accepted as molecular markers of enhanced proteasome-dependent proteolysis in cancer-related cachexia demonstrated in several types of experimental models." (PMID 32938372, 2020).
Cachexia (continued). "Paradoxically, KD did not reverse the increased expression of atrophy markers Trim63, Foxo1 and Fbxo32 in gastrocnemius muscle, which suggests that ketones exert pro‐anabolic effects even in the presence of increased catabolism in cachexia." (PMID 38632714, 2024).
Skeletal muscle atrophy (62 papers, 2009 to 2025). The presence of skeletal muscular atrophy (which is also known as amyotrophy). "MuRF1 and Atrogin1 are muscle-specific ubiquitin ligases encoded by Trim63 and Fbxo32, respectively, and are recognized as representative biomarkers of muscular atrophy." (PMID 37049603, 2023). "We found that 6- and 4.8-fold upregulation, respectively, of Fbxo32 and Trim63 was sufficient to reduce the ES to −3.89 (95% CI: −4.45 to −3.32) for the muscle fiber cross-sectional area and the development of skeletal muscle atrophy." (PMID 40331994, 2025). "As expected, GA suppressed the Dex-induced increase in the expression of Trim63 and Fbxo32, muscle-specific ubiquitin ligase genes involved in muscular atrophy." (PMID 37049603, 2023). "In this context, the E3 ubiquitin ligase of the TRIM family MuRF1/TRIM63 has aroused growing interest for its key role in the development of skeletal muscle atrophy." (PMID 32933049, 2020). "In addition, we analyzed the expression of two documented effectors of muscular atrophy, namely Fbxo32 (Atrogin-1) and Trim63 (MuRF1)." (PMID 26919175, 2016). "Therefore, we measured the expression levels of Trim63 and Fbxo32 in a Dex-induced muscular atrophy model to investigate whether GA suppresses muscular atrophy in skeletal muscle cells." (PMID 37049603, 2023). "Their target genes, including FBXO32 (also known as MAFbx/Atrogin-1), TRIM63 (also known as MuRF1), CTSL, and BNIP3, are commonly upregulated in various models of skeletal muscle atrophy, and their upregulation accelerates protein degradation." (PMID 38540418, 2024). "Our investigation of STZ-induced skeletal muscle atrophy revealed that the expression of FBXO32, TRIM63, and FoxO3a genes was more significant in fast-twitch muscle fibers (EDL) than in slow-twitch muscle fibers (soleus)." (PMID 38020198, 2023). "However, only high-dose AM was able to improve gastrocnemius muscle atrophy in the model mice, with Coll, MSTN, and YY1 being phenotypes of skeletal muscle atrophy; FBXO32 and TRIM63 were indicators of protein synthesis." (PMID 39239655, 2024).
cardiac hypertrophy (31 papers, 2011 to 2025). "Consistent with an LOF mechanism for TRIM63 variants, mice with double knockouts for both TRIM63 and TRIM55 exhibited severe cardiac hypertrophy." (PMID 39337275, 2024). "Trim63 inhibits cardiac hypertrophy and protects against cardiac infarction through degradation of tropnin I, PKCε and c-Jun." (PMID 25599194, 2015). "Similarly, transgenic mice expressing mutations in Trim63, the gene encoding MURF1, develop cardiac hypertrophy." (PMID 33195472, 2020).
diabetes (31 papers, 2012 to 2026). "Cn can modulate these TFs and downstream effectors (including the E3 ligases MuRF1/TRIM63 and MAFbx/atrogin-1) upon several conditions (dexamethasone, diabetes, exercise or starvation." (PMID 33466753, 2021). "This increase correlated with an increase in MAFbx/Atrogin-1, Murf1/Trim63 and Foxo3 genes expression and accordingly, the muscle-specific deletion of Klf15 in this model prevented from diabetes-induced muscle atrophy." (PMID 33466753, 2021). "FOXO family proteins play a vital role in the development of muscle atrophy by activating the ubiquitin-mediated proteolysis pathways including the regulation of FBXO32/Atrogin-1 and TRIM63/MuRF1, and dependently regulate BNIP3L and GABARAPL1 in a STZ-diabetes model." (PMID 32806520, 2020).